CD24 (CD24 molecule)
Diseases named in the same sentence as CD24 in open-access papers (continued):
Sharing a sentence is not in itself a finding about the gene and the disease.
tumor (continued). "Interestingly, exposure to PGE2 before CM collection significantly augmented the ability of tissue sample A to increase the percentage of CD44+/CD24−/EpCAM+ cells, suggesting that PGE2 enhanced fibroblast tumor promoting ability." (PMID 21957456, 2011). "CD24 is expressed in many ER+ tumor cell lines, while its expression is absent in some basal and Claudin-low cell lines." (PMID 21931769, 2011). "And even if patients’ survival was analysed only in the non-pCR group, we can find the tendency to have worse survival in cases with increased CD44+/CD24− or ALDH1+ tumour cell populations (P=0.127, 0.087, respectively; data not shown)." (PMID 21559013, 2011). "ALDHhigh/CD44+/CD24+ or ALDHlow/CD44+/CD24+ phenotypes do not appear to significantly contribute to tumor formation at low numbers of inoculated tumor cells." (PMID 21695188, 2011). "Moreover, CD44 appearance was detectable in 94% of 176d HBCEC and in 99% of 462d HBCEC, suggesting little if any changes of both, CD24 and CD44 during long term tumor culture." (PMID 19751512, 2009). "The tumours developing in the mouse injected with PE14 mammosphere cells also showed no expression of CD24 or of most lineage markers, being in agreement with the pathology, which showed an undifferentiated highly mitotic tumour." (PMID 18541018, 2008). "Finally, in cell lines that exhibit two distinct CD44/CD24 populations (for example, SUM149), all three markers are required to enrich correctly for tumor-initiating stem-like cells." (PMID 18366788, 2008). "In concordance with the higher number of CD44+CD24− cells in the DU145 cell line, NOD/SCID mice injected with 3 million DU145 cells formed tumours earlier (approximately 9 days) that were 14 times larger at 39 days than NOD/SCID mice injected with LNCaP cells (266.5 vs 18.2 mm3, respectively)." (PMID 18268494, 2008). "As the CD44+CD24− LNCaP cells formed colonies in soft agar with high efficiency, we compared the ability of the CD44+CD24−, CD44+CD24−-depleted cells, and total LNCaP cells to initiate tumours in NOD/SCID mice." (PMID 18268494, 2008). "The majority of tumors included at least a few double-negative (CD44-/CD24-) tumor cells, while a complete lack of both proteins was evident in 35% (83/240)." (PMID 18559090, 2008). "Despite growing therapeutic interest, clinical translation of CD24 targeting has been limited by tumor heterogeneity, redundancy among innate immune checkpoints, safety concerns related to physiological CD24 expression, and the absence of functional biomarker frameworks." (PMID 41972163, 2026). "Therefore, this study elucidates the mechanism by which the depalmitoyltransferase ABHD17C protects tumor cells from macrophage phagocytosis, which highlights the therapeutic potential of targeting the ABHD17C/BCL6B/CD24 signaling axis by macrophage-mediated innate immune pathway in PC." (PMID 42154583, 2026). "Moreover, the GBM tumor microenvironment (TME) is enriched in arachidonic acid (AA)-derived cyclooxygenase (COX) products prostaglandins (PG) E2 and F2α in combination with enhanced CD24 expression." (PMID 42003504, 2026). "Interestingly, and in line with our in vitro findings, these two CD271+ tumours did not contain any CD24+CD271+ cells." (PMID 40754577, 2025). "However, unlike in the Broad Institute dataset, the two tumours in this study that had significant CD271 expression did not overlap with the tumour containing CD24+ cells." (PMID 40754577, 2025). "Moreover, according to the same study, unlike CD166, CD133, CD24, CD90, CD44s and ALDH1, the expression of EpCAM and ABCG5 within tumor buds is often associated with a poor prognosis." (PMID 40564019, 2025). "Highly expressed CD24 competitively binds to ADP-ribosylation factor 6(Arf6) with G protein-coupled receptor kinase-interactor 2(GIT2) and stabilizes Arf6-GTP to activate subsequent ERK pathways, thereby significantly promoting tumor metastasis and 5-FU chemoresistance." (PMID 40486886, 2025).
tumor (continued). "Indeed, further pathological analyses showed reduction of SETD1B, CD24, N-cadherin and Ki67 following Trip treatment in the tumor xenografts, but reduction of these proteins was no longer seen with SETD1B KD." (PMID 40860182, 2025). "Interestingly, when the CD24 positivity was used together with another immune prognostic marker (CD3+ TIL status), a subgroup of NPC tumors that were positive for CD24 expression and had low CD3+ TIL in the tumor microenvironment had the worst DFS, MFS and OS." (PMID 40647395, 2025). "There was no data on CD24 expression in the tumor stroma specifically in TNBC." (PMID 39904885, 2025). "Thus, the simultaneous activation of NFκB and JAK/STAT signaling in TRIM28-deficient cells provides a plausible mechanistic link to enhanced expression of CD24/CD47, suggesting that TRIM28 modulates tumor–immune interactions through coordinated regulation of cytokine and adhesion pathways." (PMID 41303350, 2025). "CD24, a highly sialylated glycosyl-phosphatidyl-inositol (GPI) cell surface protein that interacts with sialic acid-binding immunoglobulin-like lectins (Siglecs), serves as an innate immune checkpoint and plays a crucial role in inflammatory diseases and tumor progression." (PMID 39791710, 2024). "Furthermore, TP63+ SLC7A5+ HNSCC subpopulation may resist phagocytosis by macrophages through the CD24-SIGLEC10 axis, promoting tumor escape." (PMID 39234254, 2024). "Specifically, the average tumor weights were 1.07 g for the antibody combination group and 0.33 g for the PAC-SABIs group, reflecting a unique PAC-SABIs functionality of concurrently inhibiting CD47 and CD24 signaling, coupled with their intrinsic self-assembly ability within the complex TME." (PMID 38971872, 2024). "Notably, animals treated with CD24-CAR-T cells had better tumor clearance than those treated with MOCK-CAR-T cells, but not as good as those treated with Bi-CAR-T cells." (PMID 38242888, 2024). "Previous studies have reported that the phagocytic activity of TAMs was sufficient to eradicate tumor cells, but the cancer cells were capable of evading attack by macrophages through the so called “don’t eat me” signals, including the overexpression of CD47, PD-L1, β2-microglobulin (B2M), and CD24." (PMID 38168654, 2024). "Moreover, CD90, CD49, CD44, CD24, and ALDH, in addition to EpCAM, are a few surface markers reported for the isolation of BCSCs, as they tend to have altered expression levels when compared to those of other bulk tumor cells." (PMID 38920716, 2024). "(F) Quantification of the percentage of EpCAM+Vim+CD24+, EpCAM+Vim+CD24- and pan-keratin+Vim+CD24+ cells in normal region (epithelium distant from the tumour), tumour body, and stromal region from metastatic and non-metastatic tumours in the first cohort of specimens." (PMID 37975646, 2023). "In various cancers, CD24 serves as a stress marker indicative of tumor burden, rather than a cell-specific marker, which led us to test if CD24 may serve a similar role in senescence." (PMID 37524694, 2023). "Further functional analysis indicated that CD24 degradation mediated by ASGPR‐driven LYTACs affected the signal transmission of the CD24/Siglec‐10 signal pathway, expression of related genes downstream of Siglec‐10 in macrophages, and phagocytosis of tumor cells by macrophages." (PMID 36866919, 2023). "Fourth, we did not address tumor microenvironment-and-leukocytes interaction, which may relate to CD24 presence, and did not evaluate HPV status." (PMID 38138858, 2023). "In-depth analysis of β4+ tumor cells’ phenotypic characteristics taking into consideration stemness and EMT features revealed a significantly increased proportion of E-cadherin+ and CD44+CD24- cells in patients with liver metastases compared to patients with lung or without distant metastases." (PMID 36769251, 2023).
tumor (continued). "Drugs targeting MHCI/LILRB1 axis may promote anti-tumor immune response and play a synergistic role with drugs targeting CD47-SIRPA axis; CD24-SIGLEC10 interaction blocks the cytoskeleton rearrangement required by macrophage phagocytosis and triggers the inhibitory signal transduction cascade." (PMID 37138287, 2023). "However, when we delayed administration of CD24-Fc for three days at the time of booster vaccination, there was no impact on survival rate in which tumor rejection was similar to controls." (PMID 37346042, 2023). "EpCAM+Vim+CD24+ cells were enriched in the stroma compared to the tumour body, and there was a much greater accumulation of EpCAM+Vim+CD24+ cells in the stroma of metastatic tumours compared to non-metastatic tumours." (PMID 37975646, 2023). "As CD73 is overexpressed in tumor-initiating cells (TIC) to promote stemness, and that TIC rely on OXPHOS to support tumorigenesis, we next evaluated the impact of CD73 on the metabolic fitness of putative TIC (ALDHHigh CD44+ CD24-) derived from MDA-MB-231 cell cultures." (PMID 37261423, 2023). "Investigators have identified several tumor-phagocytosis-related checkpoints, including the CD47/signal regulatory protein α (SIRPα) axis, the PD-1/PD-L1 axis, the MHC-I/leukocyte immunoglobulin-like receptor subfamily B (LILRB1) axis, and the CD24/SIGLEC10 axis." (PMID 38033495, 2023). "Staining for EpCAM and CD24 alongside the mesenchymal marker Vimentin in over 12,000 imaging fields from 74 human tumours, stratified on metastatic status, identifies cells that have undergone EMT and disseminated into the stromal region surrounding metastatic primary tumours." (PMID 37975646, 2023). "In addition, when we evaluated liver tissues of five patients with HCC, the protein expression of AKR1B10, ZNF468, annexin A2 (ANXA2), and CD24 was increased in tumor tissue compared with surrounding nontumor tissues." (PMID 35563425, 2022). "In G3 samples, CD24 and laminin were lower in Patient 4 and in contrast to the other G3 samples, while vimentin was higher in Patient 3, ECAD higher in Patient 2 and CK20 higher in Patient 4 relative to those in the non-tumour tissue and in contrast to the other G3 samples." (PMID 36362433, 2022). "The expression level of CD24 is upregulated across almost all tumor types but not normal tissues." (PMID 35978372, 2022). "Moreover, a subpopulation of TIS cells exhibited certain features of cancer stem cells, namely, elevated Nanog expression, augmented proportion of CD24+ cells and side population, epithelial-to-mesenchymal transition (EMT), and tumor formation in NOD/SCID animals." (PMID 36230727, 2022). "In addition, the high expression of CD24 in Cancer Cells affects the expression of SIGLEC10 in Dendritic Cells, Macrophages, GMP Cells, B Cells, and Mast Cells, which in turn affects immune disorders and leads to tumor immune escape responses." (PMID 36401283, 2022). "In addition, some scholars have found that CD24+/CD44+- EPCAM+ cell subsets have specific gene expression profiles, and these stemness-related cell subclones in HCC enable tumor cells to acquire great genetic richness, leading to the failure of HCC targeted therapy." (PMID 36303541, 2022). "By targeting 3′UTR of CD24 (CRC CSCs marker), miR-1185-1 negatively regulates CSC features and carcinogenesis, which was evidenced by reduced CSC frequency, colony formation, and migration ability in vitro and decreased tumor size and weight in xenograft model." (PMID 36429127, 2022). "Since tumor cells can regulate recognition signals and functionally modulate the expression of ligands for receptors on NK cells to mediate NK cell activity, we further investigated the dissimilarity in the expression of HLA-E and MICA/B in TNBC, RT-R-TNBC, and CD24−/low/CD44+ cells." (PMID 34502547, 2021).
tumor (continued). "Notably, compared to the control tumors, volume and weight of CD24 expressing SCC084/miR-146a tumors were not significantly (p-value = 0.7360) altered suggesting loss of miR-146a driven tumor formation ability." (PMID 34712602, 2021). "However, the tumor volumes were significantly increased in RT-R-MDA-MB-231 cell-injected mice compared to MDA-MB-231 cell-injected mice, and CD24−/low/CD44+ cell-injected mice showed even greater enhancement of tumor growth than RT-R-MDA-MB-231 cell-injected mice." (PMID 34502547, 2021). "Interestingly, although there was a modest correlation between case identity and LCSC marker group status, we observed that the LCSC marker group 2 cells, which concurrently expressed EPCAM, ALDH1A1, and CD24, grouped together into cell cluster and contained HCC tumor cells from multiple cases." (PMID 34140495, 2021). "Finally, the levels of mRNA transcripts of these DEGs among the purified parental CD44+/CD24- CSCs (red color), the newly converted CD44+/CD24- CSCs (blue color) and the unconverted CD44-/CD24- tumor cells (green color) from MDA-MB-231 cells were tested by RT-qPCR." (PMID 34318746, 2021). "The CD44 + CD24 + ESA + phenotype exhibited a 100-fold increase in tumor-initiating capacity versus non-tumorigenic cancer cells, gauged from a very little number of sorted cells required to produce tumors histologically similar to primary PC in immunocompromised mice." (PMID 34453639, 2021). "In addition, tumor cells express specific surface proteins such as CD47, PD-L1, MHC-I, and CD24 that prevent macrophages from attacking them and may contribute to metastasis and tumor growth." (PMID 33209523, 2020). "For instance, as few as 100 CSCs (isolated and identified as CD44+ CD24-) were able to induce tumor growth in non-obese diabetic/severe combined immuno-deficient (NOD/SCID) mice, while in a humanized mouse model (NSGTM), injection of 1000 melanoma CD71+ cells resulted in successful tumor induction." (PMID 33202648, 2020). "We then performed quantitative real-time PCR (qRT-PCR) analysis for four cell surface receptor genes (PTN, CD24, BMP7, and CADM1), because their protein products are easily detectable by molecular diagnosis and are also related to cell survival, proliferation, or tumor growth." (PMID 33298865, 2020). "Furthermore, holoclones showed high expression of CD44, while CD24 was not expressed in these clones, thus representing the well‐described tumor‐initiating CD24−/CD44high population." (PMID 31834633, 2020). "CD24+ LCSCs display enhanced levels of inducible nitric oxide synthase (iNOS), which triggers the Notch1 signaling pathway in a manner dependent on cGMP/PKG-mediated activation of TACE and upregulation of iRhom-2, further promoting self-renewal and tumor growth properties." (PMID 32466488, 2020). "Additionally, CD24-positive OC cells showed an EMT phenotype with higher invasive growth compared to non-expressing tumor cells as described for CSCs." (PMID 30717444, 2019). "For both cell line and tumor pieces, evaluation of gene expression demonstrates high endogenous expression of select mesenchymal genes (VIM, cMYC, FRA1, SNAI1 and SLUG), and low endogenous expressions of epithelial gene CD24 and mesenchymal genes TWIST and ZEB1." (PMID 30845999, 2019). "Note that, although the observed phototoxicity for cell viability of AvIR-PIT with Bio-CD44 was lower than that of AvIR-PIT with Bio-CD24, the anti-tumorigenic effect of the former was almost equal to the latter, suggesting superior effectiveness of CSC-targeting in PIT treatment on tumor control." (PMID 31787847, 2019). "We further evaluated the correlation between DAXX and CD24 expression in clinical cancer tissue (rho = 0.360, p < 0.001), indicating a significantly positive correlation between the expression of these two proteins through WB in all 106 CRC matched pairs of tumor and surrounding normal tissue." (PMID 31614769, 2019).
tumor (continued). "However, we did not detect the enrichment of CD44+CD24- cancer stem cells following ADR-induced tumor dormancy (data not shown)." (PMID 29774126, 2018). "GSI reduces mammosphere-formation and tumor growth of CD44+/CD24+ cells, but not CD44+/CD24− cells." (PMID 28445439, 2017). "Thus, the data obtained indicate that CD44+CD24- CSCs predominate in multicellular structures and are almost absent in discrete groups of tumor cells." (PMID 28977854, 2017). "Moreover, CD133+/CD24+ RCC ACHN cells showed stronger self-renewal ability compared to its CD133+ tumor cells (data not shown)." (PMID 28279221, 2017). "The stimuli related to PPARγ activity gave by Rosiglitazone and GW-9662, did not change the profile of tumor stem cells, translated by the absence of significant change in the percentage of this cell population, measured by the balance between CD24−/CD44+ expression." (PMID 28932171, 2017). "Flow cytometry assay indicated that XIAOPI formula had little influence on the distribution of CD44 and CD24, the cell surface markers for breast CSCs, indicating that the CSCs-inhibitory effects of XIAOPI formula might be attributed to the tumor microenvironment." (PMID 29109519, 2017). "Focusing on one of the most aggressive CTC type, which from the primitive tumor spreads to the CNS, we documented that CSF floating cancer cells overexpress syndecan-1, MUC-1 and, in a proportion of cases, the putative stem-cell markers CD15, CD24, CD44, and CD133 in BCLM." (PMID 28399903, 2017). "However, it is currently not known exactly how these CD44+/CD24- cells influence a whole tumor’s resistance to anti-cancer drugs." (PMID 28092266, 2017). "Here, we analyzed the expression of putative CSC markers—CD24, CD44, epithelial cell adhesion molecule (EpCAM), CD133, and nestin—by immunofluorescence, flow cytometry and quantitative PCR in 3 PDAC-derived cell lines and by immunohistochemistry in 3 corresponding tumor samples." (PMID 27414409, 2016). "Subsequently, colony formation of CD24+CD90+ tumor cells was compared with both a sorted non-CD24+CD90+ tumor cell population that was subject to live/death sorting as well as depleted of CD45+ cells, and a whole tumor cell preparation that was subject to live/death sorting." (PMID 27542270, 2016). "CD24 has no definite mechanism for signal transduction in tumor progression." (PMID 27494878, 2016). "In contrast, there was no upregulation of any protease in non-CD24+CD90+ tumor cells." (PMID 27542270, 2016). "In addition, the secondary tumors resemble the phenotype (morphology and ESA/CD44/CD24 expression profile) of the initial tumor and the tumorigenic ESA+CD44+CD24− tumor cells could be serially passaged at least four passages in vivo." (PMID 26349457, 2016). "We further demonstrate that this differentiation process toward the CD24- phenotype in the CD24+/IGF1R-KD is significantly enhanced as a result of the tumor microenvironment; the distribution of CD24- and CD24+ subsets was not affected in vitro as a result of the IGF1R-KD." (PMID 27179633, 2016). "Having established that CD24 specifically affects cisplatin sensitivity of these HNSCC lines and arguably has no bearing on their early radiation sensitivity profile, we intended to study the expression pattern of CD24 and compare it with the prominent CSC marker CD44 in HNSCC tumor sections." (PMID 27276062, 2016). "Osteosarcoma tumor macrophages also produce high motility group box 1 (HMGB1), which interacts with the receptor for advanced glycation end products (RAGE), toll‐like receptors, and CD24, resulting in tumor proliferation, invasion and angiogenesis mediated by NFκB and VEGF signaling." (PMID 28536380, 2016). "We also identified six UPRs unique to CPA-treated B16F10 tumors vs. GL261(B6) tumors that promote tumor cell survival or tissue repair and may contribute to B16F10 tumor unresponsiveness: activated UPRs KDM5B, RBL2 and SPARC; and inhibited UPRs FOXM1, CD24 and CSF2)." (PMID 27515027, 2016).